MACIR (macrophage immunometabolism regulator)
Description:
Regulates the macrophage function, by enhancing the resolution of inflammation and wound repair functions mediated by M2 macrophages. The regulation of macrophage function is, due at least in part, to its ability to inhibit glycolysis. May also play a role in trafficking of proteins via its interaction with UNC119 and UNC119B cargo adapters: may help the release of UNC119 and UNC119B cargo or the recycling of UNC119 and UNC119B. May play a role in ciliary membrane localization via its interaction with UNC119B and protein transport into photoreceptor cells.
Synonyms: C5orf30; FLJ25291
Tractability: PROTAC: ubiquitination databases record sites on it.
Gene: Protein-coding gene on chromosome 5 (103,258,388 to 103,278,660, forward strand). Ensembl gene ENSG00000181751.
Subcellular location: Cytoplasm; Cell projection, cilium
Subcellular location (Human Protein Atlas): Actin filaments; Nucleoplasm; Cytosol; Primary cilium
Gene Ontology:
Molecular function: protein binding
Biological process: negative regulation of inflammatory response; cilium assembly; negative regulation of cytokine production involved in inflammatory response; negative regulation of fibroblast migration
Cellular component: ciliary transition zone; cilium; cytoplasm; cytosol
Genetic constraint (gnomAD): Loss-of-function variants: 4 observed, 15.02 expected, observed/expected ratio (o/e) 0.27, 90% interval 0.13 to 0.61. The upper end of that interval is the gene's LOEUF score, 0.61, which puts it in group 2 of 6, group 1 being the genes least tolerant of losing a copy. Missense variants: 228 observed, 271.32 expected, observed/expected ratio (o/e) 0.84, 90% interval 0.75 to 0.94. Synonymous variants: 101 observed, 108.75 expected, observed/expected ratio (o/e) 0.93, 90% interval 0.79 to 1.1.
Homologues: Orthologues: macaque MACIR (100% identical), chimpanzee MACIR (99% identical), pig MACIR (97% identical), guinea pig MACIR (96% identical), mouse Macir (95% identical), rat Macir (95% identical), dog MACIR (84% identical), tropical clawed frog macir (79% identical), rabbit MACIR (75% identical), zebrafish macir (71% identical).
Diseases named in the same sentence as MACIR in open-access papers:
MACIR is named in the same sentence as 20 diseases in open-access papers, as found by Europe PMC text mining. Sharing a sentence is not in itself a finding about the gene and the disease. The quoted sentences say what the papers report.
autoimmune disease (2 papers, 2020 to 2021). A disorder resulting from loss of function or tissue destruction of an organ or multiple organs, arising from humoral or cellular immune responses of the individual to their own tissue constituents. "MACIR is implicated in the regulation of macrophages and autoimmune diseases." (PMID 34777295, 2021).
tumour (1 paper, 2023). "Intravascular EVTs also upregulated DKK3, C5orf30 (also known as MACIR) and CD24, which have each been shown in previous work to have roles in fetal viability, tumour invasion or immune tolerance." (PMID 37468587, 2023).
MACIR also shares sentences with these, for which no sentence is quoted: rheumatoid arthritis (4 papers); prostate carcinoma (3); liver cancer (2); adenocarcinoma (1); Arthritis (1); breast carcinoma (1); cancer (1); colon cancer (1); esophageal adenocarcinoma (1); glioblastoma multiforme (1); hepatocellular carcinoma (1); hypothyroidism (1); infection (1); lung carcinoma (1); lymph node metastases (1); non-small cell lung carcinoma (1); ovarian carcinoma (1); primary biliary cirrhosis (1).